ENSG00000293642 (novel protein)
Gene: Protein-coding gene on chromosome 6 (11,094,194 to 11,135,830, forward strand). Ensembl gene ENSG00000293642.
Gene Ontology:
Molecular function: DNA binding
Cellular component: nucleus
Homologues: Paralogues in human: POGK (38% identical), TIGD6 (20% identical), CENPB (19% identical), TIGD7 (19% identical), TIGD3 (18% identical), JRKL (18% identical), TIGD4 (17% identical), TIGD2 (16% identical), TIGD5 (16% identical), TIGD1 (15% identical), JRK (11% identical), POGZ (8% identical).